MC1R (melanocortin 1 receptor)
Diseases named in the same sentence as MC1R in open-access papers (continued):
Sharing a sentence is not in itself a finding about the gene and the disease.
melanoma (continued). "In light of the relatively broad expression of MC1R in normal tissues, it is of particular interest that MC1R reactive CTL can be generated from T cells of healthy individuals and melanoma patients (unpublished observation)." (PMID 12177778, 2002). "The radiolabeled peptide targeting MC1R, [212Pb]Pb-DOTA-Re(Arg11)CCMSH, demonstrated rapid tumor uptake, prolonged tumor retention, and injected activity-dependent survival benefit in B16/F1 melanoma-bearing immunocompetent xenografts 114​." (PMID 41510167, 2026). "MC1R, a member of the G protein-coupled receptor (GPCR) subfamily, regulates key physiological and behavioral features via melanocortin binding, making it a potential target for melanoma therapy (Guida, Guida & Goding, 2022)." (PMID 40547309, 2025). "The advantages of using MC1R-targeted [[68Ga]Ga-DOTAGGNle-CycMSHhex] PET radiotracer include a unique opportunity to harvest the excellent imaging properties of [68Ga] for high-sensitivity, tumor-specific imaging of melanoma metastases." (PMID 40430268, 2025). "Melanocortin 1 receptor (MC1-R) is expressed mainly in melanocytes, and the MC1R/cAMP/MITF axis plays an important role in the growth, survival and differentiation of melanocytes and melanoma cells." (PMID 38351314, 2024). "Many studies showed increased levels of MC1R expression on the surface of most melanomas (either primary or metastatic tissues) but not in carcinoma cell lines making it a valuable marker of melanoma cells." (PMID 37608347, 2023). "MC1R is a G protein-coupled receptor (GPCR) expressed in melanocytes and melanoma cells, whose activity is positively regulated by the peptide agonists α-melanocyte-stimulating hormone (αMSH) and adrenocorticotropin, derived from the precursor polyprotein proopiomelanocortin." (PMID 37762683, 2023). "Medium and low penetrance genes such as MITF and MC1R are more prevalent in the population, but alone, they are unlikely to result in melanoma development." (PMID 37762707, 2023). "Alpha-melanocyte stimulating hormone (α-MSH) and its receptor, melanocortin 1 receptor (MC1R), have been proposed as potential target for anti-cancer strategies in melanoma research, due to their tissue specific expression and involvement in melanocyte homeostasis." (PMID 37608347, 2023). "The other case where ACD VUS was found (MH32) has a personal history of multiple melanomas and a family history of melanoma and breast cancer and showed a non-RHC variant of MC1R (r/0), in addition to fair skin, light hair, and a history of childhood sunburn." (PMID 37958811, 2023). "Activation of melanocortin 1 receptor (MC1R) or receptor tyrosine kinase (c-KIT) by α-MSH or SCF ligands, respectively, activate signaling pathways in melanoma cells that may be modulated by plant extract or isolated plant compounds." (PMID 35889231, 2022). "Because MC1-R was observed in CTCs with CD45 expression, it may be useful as a marker of hybrid cells in ovarian cancer as it is in melanoma." (PMID 36499015, 2022). "Whereas traditional methods of regulating melanin metabolism (e.g., MC1R) are not significantly altered in melanoma, genes important for the regulation of melanosomal pH are altered in melanoma." (PMID 36483028, 2022). "Certain variants of melanocortin 1 receptor gene (MC1R), which encodes a protein that binds melanocyte‐stimulating hormone (MSH) and determines skin and hair pigmentation, confer risk for both melanoma and nonmelanoma skin cancers." (PMID 35932099, 2022). "The proliferation and differentiation of melanoblasts is regulated by regulatory factors, such as endothelin (EDN) and Wingless-type protein (WNT), and melanocortin 1 receptor (MC1R) is reported to be a major regulator of human pigmentation and a melanoma-related gene." (PMID 33672928, 2021). "Seemingly, the melanocyte specific isoform of the Melanocortin 1 Receptor (MC1R), involved in pigmentation of melanocytes, is not specific for melanoma cells, being also expressed in neuronal cells." (PMID 34207514, 2021).
melanoma (continued). "The MN carrier of MITF-E318K was a melanoma patient developing papillary thyroid carcinoma, a tumor type known to be associated with melanoma but not described before in E318K MITF carriers with melanoma; this patient carried a ‘R’ genotype for MC1R." (PMID 34573422, 2021). "In conclusion, we present a model system of melanoma development, driven by MITF-M in the context of MC1R loss of function, and independent of UV exposure." (PMID 32605315, 2020). "Finally, studies of antibody neutralization suggest that the melanocortin 1 receptor (MC1R) plays a critical role in MTII-induced PTEN upregulation and melanoma suppression." (PMID 31968661, 2020). "In the inherited form of melanoma, the primary genes involved are CDKN2A and MC1R." (PMID 32169117, 2020). "Our results suggest a non-pigmentary pathway as the main link between Parkinson’s disease and melanoma, and they do not rule out the melanocortin-1-receptor gene as an additional bridge between both diseases." (PMID 31208049, 2019). "For example, MC1R controls ultraviolet B (UVB)-induced G1-like cell cycle arrest and subsequent onset of premature senescence in melanocytes, abrogation of which contributes to melanoma development." (PMID 30787281, 2019). "The limitations of our peptides do not negate the significance of utilizing selective MC1R analogs for skin cancer, including melanoma, prevention." (PMID 30205559, 2018). "That these paracrine factors increase MC1R gene expression solidifies the central role of the MC1R/α-MSH axis in regulating melanocyte survival and overcoming the genotoxic effects of UV that lead to melanoma formation." (PMID 30205559, 2018). "This confirms that MC1R is not sufficient to promote melanoma development but contributes to an increased penetrance." (PMID 29081790, 2017). "Epidemiological studies have found that loss-of-function variants in MC1R can, in part, predict the red-hair color (RHC) phenotype (red hair, fair skin, low tan capacity and high UV sensitivity) as well as melanoma and non-melanoma skin cancer risk." (PMID 28030792, 2017). "Coinjection of 50 μg of α-MSH together with the radiopeptide significantly blocked melanoma uptake and confirmed MC1R-mediated internalization (data not shown)." (PMID 28491052, 2017). "In this study, we describe the development and biological properties of an MSH octapeptide conjugated to a non-selective photosensitizer for specific targeting of melanoma cells, via binding to MC1R followed by receptor-mediated internalization." (PMID 29146972, 2017). "We initially focused the analysis to on variants in genes known to cause familial malignant melanoma, but we did not identify any clearly causative variation in these genes (BAP1, CDK4, CDKN2A, MC1R, MITF and PTEN)." (PMID 28623311, 2017). "Inhibition of MC1R by its physiologically relevant competitive inhibitor, agouti signaling protein (ASIP), reduced melanin synthesis and morphological heterogeneity in murine B16-F10 melanoma cells." (PMID 27028866, 2016). "In the laboratory, disruption of MC1R increases oxidative damage and lowers the threshold for melanoma induction even in the absence of UV light." (PMID 26504519, 2015). "To do so we analyzed co-cultured melanocyte-keratinocyte systems derived from two siblings belonging to two melanoma prone families with a founder CDKN2A mutation and/or carrying non-functional MC1R alleles to compare global gene expression profiles." (PMID 24742402, 2014). "Melanocortin-1 receptor (MC1-R) is responsible for the cutaneous pigmentation, and, interestingly, it has been reported as being overexpressed in both melanotic and amelanotic melanomas." (PMID 23634303, 2013). "Melanocortin 1 receptor (MC1R) is associated with red hair, pale skin, freckling, and sun sensitivity and contributes to melanoma risk through both pigmentary and nonpigmentary effects." (PMID 24392023, 2013).
melanoma (continued). "Physician-measured nevi, MC1R genotype and previous non-melanoma skin cancer were the strongest predictors of early-onset melanoma in this study." (PMID 24134749, 2013). "However, the specific contribution of each MC1R variant to melanoma development via pigmentary and non-pigmentary pathways could not be evaluated in meta-analyses due to the lack of individually joint information on MC1R variants and phenotypic characteristics." (PMID 22862891, 2012). "Our novel findings point to the relevance of α-MSH/MC-1R signaling for the up-regulation of cytotoxic gene expression in melanoma patients which is impaired in patients with a non-functional MC-1R." (PMID 20126537, 2010). "The experiments were performed in human melanoma MeWo cell line, expressing the MC1R, and in NIH 3T3 cells, a murine cell line of fibroblasts not expressing the receptor." (PMID 19017395, 2008). "Flow cytometry studies showed that melanocortin 1 receptor was expressed in in vitro activated monocytes/macrophages and in the THP-1 monocytic leukaemia line at levels of about 1 in 3 to 1 in 5 of that found in melanomas." (PMID 12177778, 2002). "Permeabilized cells showed considerably stronger signalling than surface stained ones, and all three tested melanomas, including the cell surface negative BL line, stained positive with the anti MC1R mAb, while the C1R-A2 line remained negative." (PMID 12177778, 2002). "Among the melanoma lines which were positive for the S-100 mAb (12 out of 13), three did not express MC1R (FM3D, DL and 397)." (PMID 12177778, 2002). "Conversely, among the 20 melanomas which expressed MC1R, one (AA) was not positive for the S-100 marker." (PMID 12177778, 2002). "These peptide-specific CTL could also recognise HLA-A2+ melanoma cells expressing MC1R, demonstrating that the MC1R derived peptides are naturally processed and presented by MHC class I on the surface of melanoma cells." (PMID 12177778, 2002). "Since melanocytes were not stained by MC1R either in situ in the melanoma surrounding tissue or in normal naevi, we intend to detect MC1R expression in short time cultured melanocytes." (PMID 12177778, 2002). "Both the DFB and FM55 melanoma lines showed a weak but significant surface expression of MC1R while the BL melanoma line and the C1R-A2 line were completely negative." (PMID 12177778, 2002). "We therefore concluded that MC1R is expressed in the majority of melanoma cell lines but in none of the tested carcinomas or LCL, and that the expression of this receptor does not correlate with any of the other tested melanoma markers." (PMID 12177778, 2002). "Intracellular vs cell surface expression of MC1R was also analysed by flow cytometry on permeabilized and non-permeabilized melanoma and LCL lines." (PMID 12177778, 2002). "Furthermore, MC1R-directed fluorescent nanoprobes (MSH-TPE-BBT NPs) displayed enhanced tumor permeability, photophysical stability, biocompatibility, and specific accumulation in human/murine melanoma xenografts." (PMID 40497859, 2025). "To determine associations between “high” versus “low” MC1R expression, we dichotomized the continuous MC1R immunofluorescence intensity using the median score of all malignant melanomas as a cut-point, as there is no biological basis for dichotomization between high and low levels." (PMID 37790306, 2023). "However, their effect on the development of non-melanoma cancers is not well-studied, assuming that MC1R is primarily expressed in the melanocytes." (PMID 37679505, 2023). "We devised a strategy based on CRISPR-Cas9 knockout of endogenous MC1R in a human melanoma cell line wildtype for BRAF, NRAS and NF1, followed by reconstitution with epitope-labeled MC1R constructs, and functional analysis of clones expressing comparable levels of wildtype, R151C or D294H MC1R." (PMID 37762683, 2023).
melanoma (continued). "To explore whether MC1R also represses CXCL9/10/11 transcription in human melanoma, we compared the transcriptomes of MC1R-high versus MC1R-low non-RHC melanoma cases in TCGA." (PMID 37714844, 2023). "Besides providing an essential contribution to the growth of melanoma cells, the melanocortin type 1 receptor (MC1-R)—also named melanocyte-stimulating hormone receptor (MSHR)—is abundantly expressed on the surface of melanin positive primary MM and related metastatic lesions." (PMID 37765089, 2023). "In addition, small interfering RNA-mediated MITF silencing in melanoma cells significantly reduces melanin content by inhibiting TYR, TYRP-1, and MC1R, which indicates that the transcriptional activation of MITF is a promising strategy for treating hypopigmentation." (PMID 36235048, 2022). "Of all the PWAS associations recovered in this study, the most significant is the gene MC1R (Melanocortin 1 receptor; q-value = 1E−109 in non-melanoma skin cancer and q-value = 2E−53 in melanoma), which plays a central role in skin pigmentation, melanin formation and melanocyte differentiation." (PMID 34290314, 2021). "Additionally, small interfering RNA-mediated MITF silencing in melanoma cells significantly reduced melanin content by inhibiting tyrosinase, TRP-1, and MC1R, indicating that inhibition of the transcriptional activation of MITF is also a promising strategy to treat hypermelanogenic disorders." (PMID 34299326, 2021). "Interestingly, α-MSH elicits a rise of intracellular cAMP concentration in human melanoma cells with wild type MC1R but not in melanoma cells carrying mutant MC1R." (PMID 31968661, 2020). "However, how MC1R activity is modulated by UVR and why individuals with red hair are more prone to develop melanoma remain unclear." (PMID 32714859, 2020). "Numerous studies have demonstrated that inherited genetic variation in the melanocortin-1 receptor (MC1R) gene, a primary regulator of skin pigmentation, is associated with increased risk of melanoma and non-melanoma (keratinocyte) skin cancers, including basal cell and squamous cell carcinomas." (PMID 32350296, 2020). "In order to investigate the role of MITF with respect to melanoma development in varying RHC background, HA-tagged MITF was introduced via lentiviral transduction in both the WT MC1R Hermes 3C and in the compound heterozygote MC1R R160W/D294 Hermes 4C melanocytes." (PMID 32605315, 2020). "However, no clinical study has been reported for the use of MC1R analogs in melanoma imaging so far." (PMID 31163066, 2019). "Of note, EPAC rather than PKA inhibition abrogated CRE activation via MC1R in melanoma cells, supporting the hypothesis that the role of EPAC for melanocortin-induced gene expression is not restricted to the MC4R subtype." (PMID 27612207, 2016). "While α-MSH stimulates melanocyte precursor proliferation in vitro suggesting that MC1R is a melanocyte precursor growth receptor, there is conflicting in vitro evidence on a role for MC1R as a melanoma growth receptor and this possibility has also not been examined in vivo." (PMID 27028866, 2016). "The membrane bound melanocortin 1 receptor (MC1R), and the endothelin B receptor (ENDBR) are two G-protein coupled receptors that play important roles in constitutive regulation of melanocytes and their response to ultraviolet radiation (UVR), the main etiological factor for melanoma." (PMID 27582758, 2016). "Regarding MC1-R targeting, Yubin Miao and Thomas P. Quinn's extensive work is of particular interest, reporting on two generations of an NDP-α-MSH-based peptide used for melanoma imaging by single-photon emission-computed tomography (SPECT) and more recently by PET." (PMID 23634303, 2013). "Four melanomas that were recognised by mAb 9.2.27 were negative for MC1R (FM3D, DL, 397 and 8013)." (PMID 12177778, 2002).
melanoma (continued). "This is in line with observations made by others, who could not detect the MC1R protein in melanocytes from normal skin by immunohistochemistry, but could easily visualize MC1R on skin with melanoma tumour growth." (PMID 12177778, 2002). "Western blot analysis using cryo-preserved melanoma tissues derived from a metastatic lymph node also demonstrated a strong band corresponding to MC1R in both analysed melanomas, with similar intensity of expression as that observed in the in vitro cultured melanoma lines (data not shown)." (PMID 12177778, 2002). "Therefore, impaired function rather than activation of MC1R may increase the vulnerability of melanocytes to UV‐induced transformation to malignant melanoma." (PMID 35665216, 2022). "In addition, the possibility that MC1R is a growth receptor for melanoma has not been determined." (PMID 27028866, 2016). "Moreover, UV irradiation, which has been suggested to play a role in melanoma development, might up-regulate α-MSH/MC-1R signaling in the skin resulting in increased pigmentation as well as enhanced levels of cytotoxic CD8+ T cells, both involved in protection against melanoma development." (PMID 20126537, 2010). "Melanoma lines in which the expression of these molecules by cell surface staining could not be detected by the MC1R specific mAb, including the BL line, still showed strong intracellular staining in line with previously reported radiolabelled detection by hormone homologues." (PMID 12177778, 2002). "We therefore conclude that melanoma lines which do not stain for cell surface expression can still show intracellular expression of this protein, the reason why this method of intracellular staining was used in the subsequent screening of MC1R expression in tumour lines." (PMID 12177778, 2002). "In summary, the presence or absence of MC1R had little effect on the shape and motility of HBL human melanoma cells." (PMID 37762683, 2023). "Interestingly, a negative association between MC1R variants and BRAF mutations has been described for head/neck melanomas, suggesting a difference in the pathogenesis of melanomas located at different skin sites, head/neck or trunk, which could contribute to their divergent prognoses." (PMID 34356109, 2021). "Given that activation of MC1R in human melanoma cells stimulates the clearance of DNA strand breaks generated by oxidative stress, a possible involvement of MGRN1 in this MC1R-dependent genoprotective action cannot be ruled out and deserves further analysis." (PMID 33019669, 2020). "Although not studied in melanoma, α-MSH signaling through MC1R on vascular endothelial cells increases expression and phosphorylation of endothelial NO synthase and the subsequent production of nitric oxide (NO) in the mouse aorta and coronary vasculature." (PMID 27028866, 2016). "Only three of the 22 melanomas (DFW, BE and 1206) were negative for this mAb, all three of which expressed detectable levels of MC1R." (PMID 12177778, 2002). "Three melanoma cell lines (FMS, OCM3 and OCM1) were positive for a 37 kD protein, which corresponds to the expected size of MC1R, while the LCL line C1R-A2 was negative." (PMID 12177778, 2002). "Among the melanomas which were positive for the HBM45 mAb (8 out of 13), two did not express MC1R (FM3D and 397)." (PMID 12177778, 2002). "Our studies here indicate that targeting APT2 to rescue MC1R palmitoylation using ML349, rather than using the generic depalmitoylation inhibitor PALM-B, may represent an effective strategy for melanoma prevention, especially in redheads." (PMID 30787281, 2019). "While ASIP stimulates opposite effects, that is, de-differentiation of melanocytes, human melanoma and murine B16-F1 melanoma cells, and increases their migration in wound healing assays, the effect of ASIP induced MC1R signaling on melanoma colonization in vivo is not known." (PMID 27028866, 2016).
melanoma (continued). "Previously, we have demonstrated that three HLA-A2 binding nonamer peptides derived from melanocortin 1 receptor can elicit peptide-specific CTL which can recognize target cells transfected with the melanocortin 1 receptor gene and MHC class I matched melanoma lines." (PMID 12177778, 2002).